MERTK (MER proto-oncogene, tyrosine kinase)
Diseases named in the same sentence as MERTK in open-access papers (continued):
Sharing a sentence is not in itself a finding about the gene and the disease.
Cluster headache (4 papers, 2021 to 2025). A type of headache characterized by repeated attacks of unilateral pain lasting 15 to 180 minutes and associated with local autonomic signs. "The replication of MERTK as a susceptibility locus strengthens the evidence for its involvement in the pathophysiology of cluster headache and highlights it as a promising candidate for further investigation." (PMID 39560176, 2025). "Multiple studies across different populations, including European cohorts and a Taiwanese cohort, have replicated the association between variants near MERTK and cluster headache." (PMID 39560176, 2025). "Based on the results of the included GWAS studies, MERTK appears to be a consistently identified genetic locus associated with cluster headache susceptibility." (PMID 39560176, 2025). "Recently, MER proto-oncogene tyrosine kinase (MERTK), a cell surface receptor, was strongly associated with cluster headache through genetic studies." (PMID 38783191, 2024). "Among the previously reported cluster headache-associated SNPs, rs4519530 in MERTK and rs6541998 near MERTK were successfully replicated in our sample using imputation data." (PMID 36404298, 2022). "The four cluster headache susceptibility loci that were identified by this GWAS were rs113658130 near LINC01877/SATB2 (SATB homeobox 2), rs4519530 in MERTK, rs12121134 near LINC01705/DUSP10 (Dual Specificity Phosphatase 10), and rs11153082 in FHL5." (PMID 39560176, 2025). "MERTK is an interesting new candidate gene for cluster headache because it activates the cAMP-responsive element binding protein (CREB) and the CREB pathway has been implicated in timing and light entrainment of the SCN." (PMID 39560176, 2025). "MERTK gene expression was elevated in blood samples from study participants with cluster headache compared to controls." (PMID 38783191, 2024). "We identified three susceptibility loci, in CAPN2, MERTK, and SATB2, as well as one suggestive locus at CYP2C18/CYP2C19 at genome-wide level in patients with cluster headache in Taiwan." (PMID 36404298, 2022). "The discovery of increased MERTK mRNA levels and elevated Gal-3 in cluster headache patients points out the potential role of this gene in cluster headache, further supported by previous GWAS studies that also identified MERTK as a susceptibility locus for the disorder." (PMID 39560176, 2025). "As melanopsin-expressing RGCs are responsible for circadian photoreception and project to SCN and hypothalamus, MERTK may thus indirectly participate in the pathogenesis of cluster headache." (PMID 36404298, 2022). "In addition, enrichment analysis showed significant expression of MERTK in pituitary gland, which could potentially contribute to the altered hormonal expression in cluster headache." (PMID 36404298, 2022). "Two of the identified loci (MERTK and SATB2) replicated the findings of the previous cluster headache GWAS conducted in European cohorts." (PMID 39560176, 2025). "RT-qPCR was used to assess MERTK gene expression in blood, and ELISA immunoassays were used for MERTK ligand quantification in serum from study participants with and without cluster headache." (PMID 38783191, 2024).
colon carcinoma (4 papers, 2023 to 2025). "In line with our endogenous mouse model, a study of inflammation-associated colon cancer showed that Axl/MerTK deficiency led to increased tumor burden." (PMID 38673795, 2024). "We found that MerTK expression is moderately to highly increased in the gastrointestinal system during related human diseases such as celiac disease, colon carcinoma, colorectal adenocarcinoma, common variable immunodeficiency, and obesity." (PMID 38341954, 2024). "Our data showed that benzyl‐α‐GalNAc treatment decreased the molecular weight of TYRO3 and MERTK, suggesting that O‐glycans are also present in TYRO3 and MERTK in colon cancer cells." (PMID 36409270, 2023).
endothelial dysfunction (4 papers, 2023 to 2025). In vascular diseases, endothelial dysfunction is a systemic pathological state of the endothelium (the inner lining of blood vessels) and can be broadly defined as an imbalance between vasodilating and vasoconstricting substances produced by (or acting on) the endothelium. "MerTK deficiency in ECs induces both endothelial dysfunction and SMC phenotypic alterations, subsequently promoting AAAD development." (PMID 39744231, 2025). "Our data provides direct evidence that endothelial MerTK deficiency promotes endothelial dysfunction and SMC phenotypic alterations, accelerating AAAD development." (PMID 39744231, 2025). "Consistently, OSS markedly inhibited MerTK expression and induced endothelial dysfunction shown as decreased expression of endothelial nitric oxide synthase (eNOS), Gas 6 (ligand of MerTK), and transforming growth factor-β (TGF-β, anti-inflammatory cytokine)." (PMID 38646649, 2024). "In step-flow chamber, d-flow markedly inhibited MerTK expression while induced endothelial dysfunction, indicating increased expression of pro-inflammatory signaling such as NLRP3 inflammasome (NLRP3, pro-IL-1β, and cleaved IL-1β), TNF-α, and NF-κB." (PMID 38646649, 2024).
ischemia (4 papers, 2017 to 2024). A hypoperfusion of the BLOOD through an organ or tissue caused by a PATHOLOGIC CONSTRICTION or obstruction of its BLOOD VESSELS, or an absence of BLOOD CIRCULATION. "MerTK+ macrophages secrete IGF1 to promote angiogenesis, which is a crucial process for cardiomyocyte sustainability during ischemia." (PMID 39195894, 2024). "Interstitial macrophages (CD64+ MerTK+CD11b+) increased significantly as did the percent of CD45+ Ly6G+ neutrophils 1 day after the induction of left lung ischemia, despite the fact there was limited cell recruitment due to complete obstruction of the left pulmonary artery in this ischemia model." (PMID 29894584, 2018).
lymphoma (4 papers, 2020 to 2024). A malignant (clonal) proliferation of B- lymphocytes or T- lymphocytes which involves the lymph nodes, bone marrow and/or extranodal sites. "Further studies in additional lymphoma models will be required to prove the generality of these results and to elucidate in detail the underlying mechanisms that support MERTK-dependent NHL growth." (PMID 32973744, 2020). "Our results further demonstrate that MERTK is active in the phagocytosis of apoptotic lymphoma cells by macrophages and, most significantly, that SS lymphoma growth is markedly inhibited in Mertk−/− mice." (PMID 32973744, 2020). "In the present brief investigation, we tested the hypothesis that MERTK is involved in the clearance of apoptotic lymphoma cells by SS-TAMs and that it is important for the growth of aggressive, SS lymphoma." (PMID 32973744, 2020). "In the context of the proven ability of apoptotic lymphoma cells ultimately to facilitate SS tumor growth, we propose that inhibition of MERTK may be helpful in combination with apoptosis-inducing antilymphoma therapeutics." (PMID 32973744, 2020). "The present study does not elucidate the detailed mechanism(s) by which MERTK controls SS lymphoma growth." (PMID 32973744, 2020). "Absence of MERTK protein expression by murine lymphoma cells was confirmed by flow cytometry, by immunoblotting and by real-time RT-PCR." (PMID 32973744, 2020).
multiple sclerosis (4 papers, 2011 to 2026). A progressive autoimmune disorder affecting the central nervous system resulting in demyelination. "MERTK has been implicated in the pathogenesis of multiple sclerosis: patients with multiple sclerosis tend to have lower MERTK expression in the brain than healthy controls, and a number of single nucleotide polymorphisms in MERTK have been associated with multiple sclerosis." (PMID 34065321, 2021). "Fortunately, this deficiency in efferocytic clearance is treatable with recombinant TGF-β, which restored expression of MERTK and Gas6 to basal levels in multiple sclerosis patients." (PMID 34065321, 2021). "ANAPC1, a neurodevelopmental facilitator, and MERTK, a TAM receptor and multiple sclerosis risk gene, have also been proposed as candidate genes for the psychosis phenotype of 2q13 CNV carriers." (PMID 29603867, 2018). "Similarly, the use of the PPAR-γ agonist, pioglitazone, improves monocyte efferocytic function in multiple sclerosis patients, likely through the upregulation of MERTK and other efferocytic mediators." (PMID 34065321, 2021).
myeloma (4 papers, 2019 to 2023). "In the next step, we assessed if MERTK blockade could reduce cancer-induced bone loss and/or tumor progression in multiple myeloma." (PMID 36509738, 2022). "In vitro culture of MERTK knockout osteoblasts showed increased matrix mineralization in the presence of conditioned medium harvested from myeloma cells compared with osteoblasts isolated from control littermate mice expressing the receptor." (PMID 38203403, 2023). "GAS6 and MERTK expression were found to be upregulated in malignant bone marrow PC of myeloma patients compared with healthy donor samples." (PMID 38203403, 2023). "Blocking MERTK by small molecule inhibitor R992 exerted therapeutic anti-myeloma effects in an orthotopic xenograft myeloma mouse model." (PMID 38203403, 2023). "The number of GAS6+ and MERTK+ bone marrow plasma cells (BMPCs) were significantly increased in myeloma patients compared to healthy controls; whereas AXL and TYRO3 were mainly undetectable in BMPCs of both groups and also in human myeloma cell lines." (PMID 31694201, 2019). "All these data indicate that MERTK is the most important TAM receptor in proliferating myeloma cells and that GAS6/MERTK signaling regulates myeloma cell survival and resistance." (PMID 31694201, 2019). "Recently, small molecule MERTK-inhibitor R992 demonstrated anti-myeloma activity in vitro and in vivo." (PMID 31694201, 2019). "MERTK blockade decreased proliferation and induced apoptosis of human myeloma cell lines." (PMID 31694201, 2019). "This myeloma-induced bone disease could be targeted by inhibiting MERTK with R992 or other agents." (PMID 36509738, 2022). "The authors proved that GAS6, secreted by bone marrow stromal cells, activated AXL and MERTK signaling, which promoted MICA expression in myeloma cells via the NF-kB pathway." (PMID 38203403, 2023). "Blockade of MERTK on MM cells or pharmacologic targeting of GAS6 reduces myeloma burden and increases survival of mice bearing an orthotopic myeloma model." (PMID 35967396, 2022). "Additionally, downregulation of MERTK expression or therapeutic blockade of GAS6 by Warfarin resulted in reduced disease burden and prolonged overall survival in a systemic myeloma mouse model." (PMID 38203403, 2023).
nonalcoholic steatohepatitis (4 papers, 2022 to 2023). "That finding was consistent with recent data showing that MerTK+ macrophages activate HepSCs and induce nonalcoholic steatohepatitis fibrosis through upregulation of TGF-β production." (PMID 35639478, 2022).
periodontitis (4 papers, 2022 to 2025). An acute or chronic inflammatory process that affects the tissues that surround and support the teeth. "In periodontitis, targeting the pathways that regulate efferocytosis—such as the MER receptor tyrosine kinase (MerTK) and Gas6 signaling—could be a therapeutic strategy to resolve chronic inflammation, limit tissue destruction, and promote periodontal regeneration." (PMID 40005119, 2025).
Rod-cone dystrophy (4 papers, 2010 to 2023). An inherited retinal disease subtype in which the rod photoreceptors appear to be more severely affected than the cone photoreceptors. "Mutations in human MERTK can cause early-onset retinal degenerations including rod-cone dystrophy (also known as retinitis pigmentosa) and cone-rod dystrophy." (PMID 38136230, 2023). "Human recessive MERTK mutations have been associated with several phenotypes including RP, rod cone dystrophy and early onset, childhood blindness." (PMID 25517981, 2014). "In other words, inadequate function of PS at demanding RPE, ensuing cumulative failure of MerTK mediated efferocytosis, pursuant progressive expansion of innate immunity in the retina and subsequent drusen formation in Bruck’s membrane finally result in adult onset rod-cone dystrophy." (PMID 32489947, 2019).
steatosis (4 papers, 2019 to 2023). Increased lipid within the cytoplasm of cells. "Again, MERTK AA genotype remained associated with severe steatosis at multiple logistic regression." (PMID 31583026, 2019). "ADAM17 mediated MerTK cleavage in early, non-fibrotic steatosis is a protective process, presumably via decreasing MerTK’s receptor activity, which is reduced in disease progression." (PMID 36994095, 2023). "The prevalence of NAFLD was not affected by MERTK genotype (39.7% in MERTK AA vs. 44.1% in MERTK GG/GA), but severe steatosis was observed in 8% of patients with MERTK AA compared with 21% with MERTK GG/GA genotype." (PMID 31583026, 2019).
ZIKV infection (4 papers, 2022 to 2025). "To explore the role of these potential host factors in ZIKV infection of hTSCs, STBTS and EVTTS, we compared the expression of AXL, TYRO3, MERTK and TIM-1 in hTSCs, STBTS and EVTTS by qRT-PCR." (PMID 37684223, 2023).
age-related macular degeneration (3 papers, 2020 to 2024). Age-related loss of vision in the central portion of the retina (macula), secondary to retinal degeneration. "The ability to rescue phagocytosis despite loss of phagocytic receptor function may lead to broader therapeutic applications in the RPE beyond MerTK dysfunction, including an age-related decline in phagocytosis, which may contribute to age-related macular degeneration, a leading cause of blindness." (PMID 36121394, 2022).
aortic aneurysm (3 papers, 2025). A ruptured aneurysm located in the wall of the proximal portion of the descending aorta proceeding from the arch of the aorta. "Furthermore, the downregulation of endothelial MerTK (MER proto-oncogene tyrosine kinase) in human aortic aneurysms and dissections (AAAD) has been associated with decreased endothelial cell function and smooth muscle cell phenotypic alterations, promoting aneurysm development." (PMID 40507607, 2025).
astrocytoma (3 papers, 2016 to 2024). "An increased expression of GAS6 was associated with increased MERTK/AXL expression in astrocytoma patient samples." (PMID 28675785, 2017). "Another study using siRNA revealed that MerTK activated AKT and ERK in astrocytomas and MerTK inhibitors decreased the phosphorylation of both AKT and ERK in GBM cell lines." (PMID 38791148, 2024). "The same study indicates that the knockdown of AXL as well as MERTK by siRNA in the astrocytoma line G12 results in decreased AKT and ERK phosphorylations." (PMID 28675785, 2017).
bladder carcinoma (3 papers, 2019 to 2025). "MERTK was enriched in bladder cancer, cardiac muscle contraction, cytokine-cytokine receptor interaction, Fc gamma R-mediated phagocytosis, hematopoietic cell lineage, and olfactory transduction." (PMID 40093327, 2025). "Loss-of-function experiments identified a TYRO3-dependency of bladder carcinoma-derived cells both in vitro and in a mouse xenograft model, whereas AXL and MERTK depletion had only a minor impact on cell viability." (PMID 30765874, 2019). "Oncogenic dependency on members of the TAM tyrosine kinase receptor family (TYRO3, AXL, MERTK) has been reported in several cancer types, but their role in bladder cancer has never been explored." (PMID 30765874, 2019). "The TAM family of receptor tyrosine kinases (RTKs), which includes TYRO3, AXL and MERTK, has emerged as new therapeutic target in many types of cancer, but their role in bladder cancer has not yet been determined." (PMID 30765874, 2019).
Blindness (3 papers, 2014 to 2022). Blindness is the condition of lacking visual perception defined as a profound reduction in visual perception. "The cause for blindness in mutant MerTK-associated RP (mutMerTK-RP) is the failure of retinal pigment epithelial cells in diurnal phagocytosis of spent photoreceptor outer segment debris." (PMID 32765507, 2020). "Hence, deregulation of MerTK-regulated phagocytosis has been linked to diseases, ranging from cancer and rheumatoid arthritis to neurodegenerative conditions and blindness." (PMID 36121394, 2022).
Cognitive impairment (3 papers, 2021 to 2025). Abnormal cognition is characterized by deficits in thinking, reasoning, or remembering. "Moreover, we showed that astrocytic Megf10 expression correlated with dysfunctional daily life activities, BPSD, and cognitive impairment, and astrocytes are involved in synapse pruning and clearance of neuronal debris through the MEGF10/MERTK signaling pathway." (PMID 41199342, 2025).
Crohn disease (3 papers, 2021 to 2024). A gastrointestinal disorder characterized by chronic inflammation involving all layers of the intestinal wall, noncaseating granulomas affecting the intestinal wall and regional lymph nodes, and transmural fibrosis. "However, MerTK is lowly expressed in the gastrointestinal system during Crohn's disease, familial adenomatous polyposis, and ulcerative colitis." (PMID 38341954, 2024).
endometrial cancer (3 papers, 2023 to 2025). Primary or metastatic malignant neoplasm involving the endometrium (mucous membrane that lines the endometrial cavity). "MERTK is a promising therapeutic target on tumor-associated macrophages in most solid cancers, and its ligands may be attractive molecular targets for treating endometrial cancer." (PMID 37780629, 2023). "For instance, copy number variations affect the expression of key protein kinase genes, such as MERTK and MET, which have been shown to correlate with survival outcomes in endometrial cancer and renal cancer." (PMID 40396172, 2025).
fatty liver (3 papers, 2018 to 2025). "As expected, NAFLD mice treated with MERTK+/hi M2c macrophages significantly alleviated liver burden indexed by the reduction of inflammation and hepatic steatosis, even though hepatocytes ballooning was still present." (PMID 34638941, 2021). "The introduction of the MERTK+/hi M2c macrophages to the atherogenic-diet-induced NAFLD mice model have been shown to alleviate the fatty liver burden." (PMID 34638941, 2021). "Hence, our baicalin-induced MERTK+/hi M2c macrophages may have hepatoprotective properties backwards from fatty liver disease." (PMID 34638941, 2021). "Genetic variations (PNPLA3, TM6SF2, GCKR, MBOAT7, MERTK, and HSD17B13) are one of the non-modifiable risk factors for metabolic dysfunction-associated fatty liver disease (MAFLD) and MASLD." (PMID 40507973, 2025).
head and neck cancer (3 papers, 2016 to 2024). A primary or metastatic malignant neoplasm affecting the head and neck. "In this report we therefore present data from a comprehensive analysis of the role of MERTK in head and neck cancer." (PMID 27081701, 2016). "In keeping with previous studies which identified high AXL expression and AXL-mediated oncogenic properties in OSCC and head and neck cancers, we found AXL to be highly expressed in our cell lines, whereas TYRO3 and MERTK levels were barely detectable." (PMID 28118606, 2017).
hematoma (3 papers, 2023 to 2025). A hematoma is a collection of blood from a vascular structure into an extravascular space. "In mice, loss of the phagocytic receptor tyrosine kinases AXL and MerTK not only reduced phagocytosis but also decreased alternative activation of macrophages after ICH, which resulted in delayed hematoma clearance and neurological recovery." (PMID 37601043, 2023).